CD4 (CD4 molecule)
Diseases named in the same sentence as CD4 in open-access papers (continued):
Sharing a sentence is not in itself a finding about the gene and the disease.
atherosclerosis (continued). "To investigate an association between the severity of HIV infection and changes in surrogate markers of atherosclerosis or metabolic parameters, we analysed correlations between all metabolic parameters and IMT versus CD4+ T cell count and HIV viral load." (PMID 30998801, 2019). "Along this line, it is well known that both CD4+ and CD8+ T cells are involved in atherosclerosis development." (PMID 30583563, 2018). "In the context of atherosclerosis, prior reports provided evidence of LDL-reactive CD4+ and CD8+ T cells." (PMID 29091929, 2017). "In contrast, TGF-β, which is produced by many cells, such as CD4+CD25+Foxp3+ Tregs, is a protective effector in atherosclerosis." (PMID 28903402, 2017). "In case of atherosclerosis, local abundance of lipoprotein-derived atherosclerotic antigens may constantly cause the activation of APC, antigen presentation and, thus, promote persistent local CD4+ T cells re-activation and as a consequence, upregulated cytokine production." (PMID 28536468, 2017). "Protein phosphatase 5 (PP5) is a stress induced inhibitor of T cell ERK and JNK signaling in “senescent” CD4+CD28− T cells, also characterized by DNA demethylation and altered expression of genes that promote atherosclerosis." (PMID 28239687, 2016). "Several observations support the involvement of CD4+ TH cells in the pathogenesis of vascular inflammatory diseases like AAV and atherosclerosis." (PMID 25352848, 2014). "Atherosclerosis was ameliorated in the hyperlipidemic mice and CD19+ B cells, CD4+ and CD8+ T cells were reduced in atherosclerotic lesions." (PMID 23560095, 2013). "Among CD4+Tcell, TEM and related TEM subpopulations are those strongly correlated with the extent of atherosclerosis in carotid and coronary districts." (PMID 23130116, 2012). "CD4+ and CD8+ T cells as well as PCNA+ cells are cellular markers of inflammatory responses and active proliferative activity in atherosclerosis." (PMID 22238605, 2012). "However, as CCR7 is expressed on several lymphocytes, including cells that express adhesion molecules required for homing to nonlymphoid tissues, the deficiency of CCR7 could also impair the trafficking of cells other than CD4 lymphocytes during atherosclerosis." (PMID 23130116, 2012). "Using a murine model of atherosclerosis, we demonstrate that this process is orchestrated by a progressively disrupted perivascular immune milieu characterized by an expansion of CD44+ memory CD4+ T cells at the expense of CD44− naive CD4+ T cells." (PMID 41143276, 2025). "In a study of atherosclerosis, RMT1-10 could specifically expand TIM1+ IgM+ B1a cells and reduce the number of CD4+ CD8+ T cells, thereby reducing arterial inflammation and inhibiting the progression and development of atherosclerosis." (PMID 40075055, 2025). "CD4+ T helper cells are critical in CVD, particularly in atherosclerosis and hypertension." (PMID 39736852, 2025). "Additionally, CD8+ Tem and Tcm cells accumulate in greater number than CD4+ Tem and Tcm cells, indicating a more pronounced role for CD8+ T-cells in the development of vein graft atherosclerosis." (PMID 40737954, 2025). "In addition, crosstalk between CD4+ T-lymphocytes and B-lymphocytes via MHC II and CD40 molecules increases development of atherosclerosis." (PMID 40498464, 2025).
atherosclerosis (continued). "Our data showing Xcr1+ cDC1-dependent CD4 and CD8 T cell activation in atherosclerotic plaques is in line with the new paradigm for cDC1s as a platform for both CD4 and CD8 T cell responses in the novel context of atherosclerosis." (PMID 40934103, 2025). "In a hyperlipidemic mouse model, the importance of MHC-II in atherosclerosis was depicted, as mice deficient in this protein had a twofold increase in CD8 cells while no CD4 activation, thus resulting in higher proatherogenic development." (PMID 39944697, 2025). "Limited research has been conducted on the association between VZV and atherosclerosis in PLWH, despite the high frequency of VZV reactivation in PLWH both with and without significant CD4+ cell depletion." (PMID 39000373, 2024). "Recent studies have found that deletion of CCR7 not only leads to reduced plaque content in mice, but also results in disturbed access of T cells to and from the site of plaque inflammation.The ApoE-/- mice lacking CD4+ T cells show reduced atherosclerosis." (PMID 39399488, 2024). "Together, this indicates an anti-inflammatory role for NUAK2 signaling in adipocytes and CD4+ T cells, but a study in the context of atherosclerosis is lacking so far." (PMID 38892400, 2024). "CD4+ T-cell subpopulations (T helper [TH] 1,190 TH2,191 TH17,192 CD4+ T regulatory [Treg] cells, and cytotoxic T cells) are present in atheroma and influence the different stages of atherosclerosis." (PMID 38781301, 2024). "Specifically, atherosclerosis is reduced in mouse models lacking CD4 T cells, illustrating a significant role of CD4 T cells in the pathogenesis of atherosclerosis and SLE." (PMID 39603656, 2024). "Finally, we defined the genes supporting the overlap between the atherosclerosis and PSA subsets in C3 and C5 of both CD4+ and CD8+ T cells." (PMID 38665903, 2023). "The analysis revealed that 18 types of immune cells, including CD8 + Tem, macrophages, MDSCs, Bm, CD8 + T cm, Tfh, γδT, CD4 + Ta, CD56 + NK, NKT, Ba, Treg, DCa, Th1, CD8 + Ta, NK, Bi, and Th17, were different between patients with atherosclerosis and controls in the GSE28829 dataset." (PMID 37649719, 2023). "Based on the accumulation of plaque-enriched CD4+ and CD8+ T cell clonotypes, we hypothesized that human atherosclerosis could be characterized as an autoimmune-driven T cell response." (PMID 38665903, 2023). "In the early stages of atherosclerosis, the recruitment of CD4+ T cells with a regulatory phenotype (Treg) rather than an effector phenotype (Teff) is predominant." (PMID 37109221, 2023). "In this context, we will focus on the roles of CD4+ and CD8+ T cells in atherosclerosis." (PMID 38004268, 2023). "For example, it has been proven that at least three separate pathways, mediated by increased oxidative stress, pro-inflammatory CD4 + CD28null T-cells, and monocyte dysregulation each play a role in ARD-mediated atherosclerosis and coronary microvascular disease." (PMID 37324629, 2023). "Our results suggest that CD4+ and CD8+ T cells from AS+ PLWH play a role in cell adhesion, apoptosis and migration processes involved in atherosclerosis, and these atherogenic processes are mediated by the upregulated PI3K-AKT, mTOR, and cytoskeletal signaling pathways." (PMID 36131068, 2022). "Our recent studies showed that CD4+LAP+ and CD4+CD25+ Tregs are suppressed in ACS and that CD4+LAP+ and CD4+CD25+Foxp3+ T cells induced by nasal-oxidized low-density lipoprotein suppress effector T cell responses and attenuate atherosclerosis in ApoE−/− mice." (PMID 36405994, 2022).
atherosclerosis (continued). "In HAART-naive PLWH, a lower CD4 count indicates severe immunosuppression, and the HIV may promote the formation of atherosclerosis by activating endothelial cells, as well as immune cells, and increasing the number of atherogenic immune cells in vivo." (PMID 34983408, 2022). "First, elucidation of the critical roles of various subsets of CD4+ helper T cells will help determine which T cells are “friend” rather than “foe” in atherosclerosis." (PMID 35428200, 2022). "Fol-B cells are the predominant B2 population that produces atherogenic IgG that triggers MHC-II expression, therefore recruiting CD4+ T cells as well as upregulation of proinflammatory cytokines TNF-α, IL-1β, and chemokines MCP-1, henceforth exacerbating atherosclerosis." (PMID 36361845, 2022). "A protective role of antigen-specific CD4+ T cells can also be derived from the observation that a genetic knock-out for MHC-II, which abrogates antigen-recognition and -presentation, promotes de novo atherosclerosis." (PMID 33669769, 2021). "In addition to IFN-α, several triggers of atherosclerosis, including thrombin and IFN-γ, can induce CMPK2 expression, which was elevated in CD4+ T cells and CD14+ monocytes isolated from SLE patients compared to those isolated from controls." (PMID 33874983, 2021). "When CD4+ T cell activation is inhibited by a lymphocyte-specific protein tyrosine kinase (LCK) inhibitor, the accumulation of cholesterol and macrophages is decreased, and the content of smooth muscle cells is increased in a mouse model of atherosclerosis." (PMID 33505215, 2021). "In addition to IFN-α, several triggers of atherosclerosis, including thrombin and IFN-γ, can induce CMPK2 expression, which is elevated in CD4+ T cells and CD14+ monocytes isolated from SLE patients compared to those isolated from controls." (PMID 33874983, 2021). "Previously, it was shown that absence of PD-1/PD-L1/2 signaling can aggravate atherosclerosis by enhancing T cell proliferation, activation of both CD4+ as CD8+ T cells, and more specifically by increasing pro-atherogenic IFNγ production by T cells." (PMID 34790707, 2021). "CD4+ Th1 responses, directed by the Th1 master T-box transcriptional regulators T-BET and (to some extent) Eomesodermin (EOMES) are the most prevalent Th subset in atherosclerotic plaques and promote atherosclerosis progression and severity." (PMID 33483751, 2021). "Given this, combined with the fact that circulating monocyte numbers correlate with atherosclerosis progression, it was unexpected that the increased monocyte and CD4+ T cells did not aggravate atherosclerosis in Apoe-/- Mc1re/e chimeric mice." (PMID 34868038, 2021). "Activated CD4+ and CD8+ T cells promote the initiation of atherosclerosis and also drive the progression towards vulnerable plaques that may trigger myocardial infarction or ischemic stroke upon rupture." (PMID 32872393, 2020). "Lastly, utilization of a T cell restimulation assay and an innovative MHC-II-tetramer loaded with an ApoB-epitope enabled direct detection of ApoB-reactive CD4+ T cells (ApoB+ T cells) in human blood from subjects with and without atherosclerosis." (PMID 33266027, 2020). "The expression of PD-1 proteins was seen on subsets of the CD4+ T cell phenotype, CD4+CXCR5+ T cells, in CAD patients and was found elevated on CD8+ T cells isolated from plaques of femoral arteries and peripheral blood in patients with atherosclerosis." (PMID 33142805, 2020). "The lack of specificity of current CD4 T cell depletion strategies prevented us from directly assessing the importance of the reduction in CD4 T cell activity on atherosclerosis." (PMID 31998318, 2019). "A possible crosstalk between CD4 T cells and B cells in non-lesion areas has been suggested in atherosclerosis." (PMID 31998318, 2019). "Although statistically not significant, a fraction of CD4+ T- and NK-cells tended to decrease in atherosclerosis patient." (PMID 28698603, 2017).
atherosclerosis (continued). "There is significant evidence that HIV infection is associated with chronic systemic and vascular inflammation even in patients on stable HAART with preserved CD4 counts and HIV RNA levels < 50 copies/ml, and these patients also have a greater burden of subclinical atherosclerosis." (PMID 25187084, 2014). "We also found that CD4+LAP+ Treg cells induced by nasal ox-LDL produce an amount of TGF-β and may play a protective role in atherosclerosis." (PMID 24385687, 2013). "Thus, proinflammatory cytokines produced by macrophages, dendritic cells, CD4+ and CD8+ T cells promote the development and progression of atherosclerosis as positive regulators." (PMID 22238605, 2012). "We recently evaluated the CD8+ T cell response to hypercholesterolemia in an Apoe−/− mouse model leading to the conclusion that initial atherosclerosis is characterized by a CD8+ T cell response which was more rapid and stronger than the corresponding CD4+ T cell response." (PMID 22479479, 2012). "However, ABT treatment decreased circulating CD4+CD28null T cells; thus, ABT may inhibit atherosclerosis by reducing these cells." (PMID 38627782, 2024). "The univariable binary logistic regression analyses showed that female sex, age > 50 years old, HIV-1 RNA over 105 copies/mL, receiving ART regimens containing AZT and CD4/CD8 ratio < 0.3 were shared risk factors for raised TC, LDL-C, and non-HDL-C, which formed the core of atherosclerosis directly." (PMID 37705002, 2023). "Compared to those without atherosclerosis, patients with atherosclerosis were on average 5.35 years older (53.86 vs. 48.51, p < 0.001) and had a higher prevalence of smoking (63.23% vs. 39.12%, p = 0.020) and a CD4/CD8 ratio below 0.7 (44.23% vs. 29.02%, p = 0.043)." (PMID 36627565, 2023). "Our study identifies a new function of CD69 by promoting PD-1 expression in CD4 + T lymphocytes after the engagement with oxLDL that might be responsible for the exacerbated activation state found in the absence of CD69 in the atherosclerosis model." (PMID 35930205, 2022). "Such ApoB-reactive (ApoB+) CD4+ T cells mainly comprise Tregs, which confer atheroprotective properties in healthy humans, but coexpress TFs typical of proatherogenic TH1 or TH17 cells in individuals with subclinical atherosclerosis as determined by carotid ultrasound." (PMID 35097027, 2021). "For example, a study showed that oral or nasal administration of HSP60 inhibits atherosclerosis formation, just as the adoptive transfer of HSP60-specific CD4+CD25high cells induced through HSP60-loaded DCs in vitro does, indicating the antigen specific Tregs could be induced by DCs in vivo." (PMID 32849502, 2020). "CD4+ T cell exosomes enhanced cholesterol accumulation and induced the production of the proinflammatory cytokine TNF-α in cultured human monocytes, which suggests that T cell exosomes might play a role in the pathogenesis of atherosclerosis." (PMID 31615107, 2019). "However, the total abrogation of CD4+ T cells results in the absence of proinflammatory and anti-inflammatory cell populations with opposite influences on atherosclerosis." (PMID 31653058, 2019). "CD4+ T cell exosomes can induce TNF-α in monocytes, which may contribute to atherosclerosis." (PMID 31615107, 2019). "Indeed, regulatory T-cells (Tregs), which constitute 5-10% of all CD4+ T lymphocytes in the peripheral blood, have been shown to be athero-protective and could function as new targets in both CVD and atherosclerosis." (PMID 31849973, 2019). "Similarly, there is increasing evidence that both CD4+ and CD8+ TC are involved in atherosclerosis." (PMID 30064449, 2018).
atherosclerosis (continued). "Furthermore, we hypothesized that antibodies against CMV and hHSP60 were related to the presence of CD4+CD28null T cells in AAV and related to the presence of atherosclerosis." (PMID 28084533, 2017). "However, although emerging evidence shows a role for CD4+ T cells and macrophage phenotype switch in atherosclerosis, no study has addressed this significance in PAD." (PMID 24744903, 2014). "However LDL immunization was effective against atherosclerosis even in CD4/apoE double knockout mice, suggesting CD4+ T cells are not important mediators of the beneficial effect of LDL immunization." (PMID 22347402, 2012). "On the other hand, intranasal immunization of apoE(-/-) mice with a p210-CTB fusion protein preparation reduced atherosclerosis by 35% with increased IgG titers against p210 and CD4+ T regulatory cells without further elucidation of the role of either immune response." (PMID 22347402, 2012). "The absence of CD4+ T cells in apoE‐knockout mice could ameliorate atherosclerosis." (PMID 36988256, 2023). "For example, anti-CD3 treatment in mice induces CD4+LAP+ Tregs and attenuates the initiation of atherosclerosis but not the progression of established atherosclerosis." (PMID 36405994, 2022). "However, CD4+ T cells recognizing epitopes derived from unmodified apolipoprotein B100 (ApoB) has also been found, first in human ApoB100 transgenic mice, and more recently in the blood from subjects with and without atherosclerosis, by using an MHC class II-tetramer loaded with an ApoB epitope." (PMID 33805071, 2021). "Not surprisingly, within the CD4+ and CD8+ T cell compartment from aged atherosclerotic mice, we found hallmarks of T cell aging and a local and systemic increase in the frequency of Th1 cells, which can contribute to the accelerated atherosclerosis progression in aged mice." (PMID 40603813, 2025). "Additionally, CD69 promotes programmed cell death 1 (PD-1) expression in CD4+ T lymphocytes after engagement with oxLDL, which may be responsible for the exacerbated activation state found in the absence of CD69 in an atherosclerosis model." (PMID 39817455, 2025). "Notably, at the point of sacrifice in our atherosclerosis experiment we did not observe restriction of TFH cells by IFNγ-B cells, but we did demonstrate that IFNγ-B cells were able to promote anti-inflammatory CD4+ T cells." (PMID 35187121, 2022). "However, CD4+CD25+FoxP3+ Treg cells or CD8+CD122+ Treg cells showed a lack of selectivity for the 20μg dosed-group, suggesting that they are not involved in the protective effect on atherosclerosis." (PMID 29091929, 2017).